TYRO3 (TYRO3 protein tyrosine kinase)
Description:
Receptor tyrosine kinase that transduces signals from the extracellular matrix into the cytoplasm by binding to several ligands including TULP1 or GAS6. Regulates many physiological processes including cell survival, migration and differentiation. Ligand binding at the cell surface induces dimerization and autophosphorylation of TYRO3 on its intracellular domain that provides docking sites for downstream signaling molecules. Following activation by ligand, interacts with PIK3R1 and thereby enhances PI3-kinase activity. Activates the AKT survival pathway, including nuclear translocation of NF-kappa-B and up-regulation of transcription of NF-kappa-B-regulated genes. TYRO3 signaling plays a role in various processes such as neuron protection from excitotoxic injury, platelet aggregation and cytoskeleton reorganization. Also plays an important role in inhibition of Toll-like receptors (TLRs)-mediated innate immune response by activating STAT1, which selectively induces production of suppressors of cytokine signaling SOCS1 and SOCS3. (Microbial infection) Acts as a receptor for lassa virus and lymphocytic choriomeningitis virus, possibly through GAS6 binding to phosphatidyl-serine at the surface of virion envelope. (Microbial infection) Acts as a receptor for Ebolavirus, possibly through GAS6 binding to phosphatidyl-serine at the surface of virion envelope.
Synonyms: BYK; DTK; RSE; SKY; TIF; Brt; Etk-2; Rek
Tractability: Small molecule: a high-quality ligand is known; it belongs to a druggable protein family. Antibody: UniProt places it where antibodies can reach, with medium confidence; UniProt predicts a signal peptide or a membrane-spanning region; its Gene Ontology location is reachable by antibodies, with medium confidence. PROTAC: ubiquitination databases record sites on it; its protein half-life has been measured; a small molecule that binds it is known.
Target class: Tyrosine protein kinase Axl family; Protein Kinase; Kinase; TK protein kinase group; Enzyme
Gene: Protein-coding gene on chromosome 15 (41,557,675 to 41,583,589, forward strand). Ensembl gene ENSG00000092445.
Subcellular location: Cell membrane
Pathways (Reactome):
Disease: Dengue Virus Attachment and Entry
Gene Ontology:
Molecular function: phosphatidylinositol 3-kinase binding; protein binding; protein tyrosine kinase activity; virus receptor activity; transmembrane receptor protein tyrosine kinase activity; ATP binding; protein kinase activity
Biological process: positive regulation of viral life cycle; apoptotic cell clearance; cell adhesion; cell migration; cell surface receptor protein tyrosine kinase signaling pathway; forebrain cell migration; negative regulation of inflammatory response; negative regulation of innate immune response; negative regulation of neuron apoptotic process; negative regulation of toll-like receptor signaling pathway; nervous system development; neuron cellular homeostasis; ovulation cycle; phagocytosis; phosphatidylinositol 3-kinase/protein kinase B signal transduction; platelet activation; platelet aggregation; positive regulation of phosphatidylinositol 3-kinase/protein kinase B signal transduction; secretion by cell; signal transduction; spermatogenesis; substrate adhesion-dependent cell spreading; symbiont entry into host cell
Cellular component: cell surface; endoplasmic reticulum membrane; endosome membrane; nuclear envelope; nucleus; plasma membrane; receptor complex
Genetic constraint (gnomAD): Loss-of-function variants: 36 observed, 84.11 expected, observed/expected ratio (o/e) 0.43, 90% interval 0.33 to 0.56. The upper end of that interval is the gene's LOEUF score, 0.56, which puts it in group 2 of 6, group 1 being the genes least tolerant of losing a copy. Missense variants: 787 observed, 1,048.4 expected, observed/expected ratio (o/e) 0.75, 90% interval 0.71 to 0.8. Synonymous variants: 354 observed, 410.93 expected, observed/expected ratio (o/e) 0.86, 90% interval 0.79 to 0.94.
Homologues: Orthologues: chimpanzee TYRO3 (99% identical), macaque TYRO3 (99% identical), pig TYRO3 (94% identical), dog TYRO3 (90% identical), guinea pig TYRO3 (90% identical), rat Tyro3 (89% identical), mouse Tyro3 (89% identical), rabbit TYRO3 (84% identical), tropical clawed frog tyro3 (58% identical), zebrafish tyro3 (48% identical). Paralogues in human: AXL (41% identical), MERTK (39% identical), ROS1 (24% identical), MST1R (24% identical), MET (23% identical), INSR (21% identical), TIE1 (21% identical), TEK (21% identical), IGF1R (21% identical), INSRR (21% identical), EPHA1 (20% identical), KDR (20% identical), and 41 more.
Diseases named in the same sentence as TYRO3 in open-access papers:
TYRO3 is named in the same sentence as 130 diseases in open-access papers, as found by Europe PMC text mining. Sharing a sentence is not in itself a finding about the gene and the disease. The quoted sentences say what the papers report.
melanoma (28 papers, 2012 to 2025). A malignant, usually aggressive tumor composed of atypical, neoplastic melanocytes. "For example, TYRO3 has been implicated in the proliferation, tumorigenesis, chemoresistance, and motility of melanoma cells." (PMID 38703893, 2024). "In a survey of melanoma-derived cell lines we found that Tyro3 was ubiquitously present, but high levels of Axl were selective for metastatic growth phase (MGP) lines, with the exception of IgR3." (PMID 36989239, 2023). "Quantitation from multiple Western blot results showed the expression of Tyro3 to be highest in melanoma, glioma and kidney cancer cells." (PMID 31766614, 2019). "Downregulation of TYRO3 significantly inhibited the proliferation of melanoma cells, while the ectopic expression of TYRO3 inhibited BRAFV600E induced senescence and enhanced cell proliferation." (PMID 31416288, 2019). "In cancer, some recent studies have shown Tyro3 to be strongly expressed in cancer cell lines from melanoma, ovarian, hepatocellular, thyroid, colon and bladder cancers." (PMID 31766614, 2019). "Tyro3 shRNA knockdown promoted apoptosis and decreased anchorage-independent growth in e.g. melanoma cells." (PMID 31766614, 2019). "Several studies have shown that Tyro3 is significantly upregulated in thyroid cancer cells and melanoma cells, though few studies have examined the importance of Tyro3 overexpression." (PMID 29386018, 2018). "Phosphorylation of TYRO3 has been demonstrated in melanoma, breast cancer, and leiomyosarcoma cell lines and in chronic lymphocytic leukemia and schwannoma patient samples." (PMID 30501104, 2018). "Derivatives of the A2058 melanoma cell line with siRNA-mediated TYRO3 inhibition exhibited increased apoptosis relative to cells expressing a control siRNA in response to treatment with cisplatin, temozolomide, or docetaxel." (PMID 30501104, 2018). "These include two different mouse monoclonal antibodies raised against the extracellular domain of human TYRO3 that block GAS6-induced TYRO3 signaling in melanoma cells and have low cross-reactivity with MERTK and AXL." (PMID 30501104, 2018). "Regulation of cell-type specific effectors downstream of TYRO3 has also been reported in specific tumor types, including Microphthalmia-associated transcription factor (MITF) in melanoma 48] and alpha-fetoprotein (AFP) in hepatocellular carcinoma." (PMID 30501104, 2018). "TYRO3 induces MITF-M expression in a SOX10-dependent manner in melanoma cells, while other studies showed the anti-correlation between MITF and AXL in melanoma cells." (PMID 27102439, 2016). "Apart from ovarian cancer Tyro3 was suggested as target in breast cancer, melanoma and thyroid cancer." (PMID 27486820, 2016). "The transforming potential of Tyro3 has been demonstrated by its ability to induce anchorage-independent growth on soft agar in fibroblastic cell lines and malignant melanoma cells." (PMID 22606290, 2012). "We acquired multi-omics data from the cleavage-resistant and WT TYRO3 variants and utilized the DMPA to shed light on the unknown cleavage-associated signaling pathways of TYRO3 in melanoma cells." (PMID 38703893, 2024). "To understand the signals that impel primary melanoma tumors to become metastatic, we determined the expression of TAM family members (Axl, Tyro3 and MerTK) in melanoma cell lines including vertical growth phase (VGP) and metastatic growth phase (MGP) using immunoblotting." (PMID 36989239, 2023). "Compared to melanocytes, all eight melanoma cell lines present increased expression of Tyro3." (PMID 36989239, 2023). "Finally, overexpression of TYRO3 enabled melanoma cells to overcome senescence downstream of oncogenic BRAF(V600E) signaling." (PMID 30501104, 2018). "It was recently indicated that Tyro3 expression increases survival of malignant melanoma cells." (PMID 27486820, 2016).
melanoma (continued). "Interestingly, melanomas harboring Tyro3 display a higher proliferation rate in more differentiated cells, and this is consistent with the roles of Tyro3 and Axl in prostate cancer metastasis, as cited previously." (PMID 25344858, 2014). "In addition, when injected into nude mice, Rat1b fibroblasts overexpressing Tyro3 stimulate tumor formation and knockdown of Tyro3 in malignant melanoma cells decreases their proliferation." (PMID 22606290, 2012). "Notably, a study revealed that TYRO3 knockdown suppressed melanoma cell migration and invasion, while TYRO3 overexpression led to the opposite outcomes via activation of the tyrosyl-phosphorylation of ACTN4, a member of the actin binding protein family involved in cancer cell motility." (PMID 32018224, 2020). "Some studies have found that the expressions of Tyro3, Ax1, MERTK and their ligands of MDSCs in tumor-bearing (melanoma) mice are significantly up-regulated, which can inhibit the ability of T cells to migrate to tumor draining lymph nodes." (PMID 37221594, 2023). "TYRO3 has been found to be upregulated in various cancers, including AML, CML, multiple myeloma, melanoma, as well as uterine endometrial cancers." (PMID 35884425, 2022). "Another strategy that melanoma cells use to adapt to drug-induced stress is by upregulating autophagy, a result of ER stress and TAM receptor protein tyrosine kinases (TYRO3, AXL, MER) pathway activation." (PMID 33922284, 2021). "This is consistent with earlier results demonstrating that melanoma cells expressed very little AXL and relied more on the MER and TYRO3 kinases." (PMID 32042425, 2020). "TYRO3 was identified as a positive regulator of MITF expression in murine melanoma cells and was upregulated in 20 of 40 melanoma cell lines tested relative to other types of human cancer cell lines." (PMID 30501104, 2018). "Another study analyzed active RTKs in melanoma cell lines through measurement of their level of tyrosine phosphorylation and found that AXL, TYRO3 and MER were among the RTKs with the highest overall activation level." (PMID 27102439, 2016). "In vivo, intravenous injection of treated melanoma cells revealed that GAS6 + macrophage co-culture and GAS6 treatment significantly increased tumor fluorescence intensity and weight compared to controls, whereas TYRO3 inhibition suppressed tumor growth." (PMID 41034991, 2025). "Nevertheless, previous publication reported that downregulation of TYRO3 by siRNA mediated knockdown was able to prevent melanoma cell migration and invasion which would not fit into the proposed model of metastatic suspension cells in CTCs." (PMID 39425449, 2024). "In the present study, we found that melanoma cell lines present variable protein levels of Axl and Tyro3; interestingly, MerTK is not noted at detectable levels in any of tested MGP (metastatic growth phase) cell lines." (PMID 36989239, 2023). "This suggests that Tyro3, Ax1 and MERTK control the function of MDSC and are expected to be pharmacological targets for regulating MDSC-mediated immunosuppression in patients with melanoma." (PMID 37221594, 2023). "Interestingly, when drugs inhibit the expression of Tyro3, Ax1 and MERTK in vivo, melanoma growth slows down, CD8+T cell infiltration increases, and anti-PD-1 checkpoint inhibitor immunotherapy is enhanced." (PMID 37221594, 2023). "Tyro3, Axl, and MerTK control myeloid-derived suppressor cell (MDSC) functionality, regulate MDSC-mediated immune suppression and augment anti-PD-1 therapy in melanoma patients, which highlights the role of these molecules in antitumor therapy." (PMID 36059952, 2022). "The TAM family are implicated in regulating MDSC function, since increased MDSC expression of TYRO3, AXL and MERTK and their ligands was detected in a syngeneic mouse model of melanoma, and circulating MERTK+ and TYRO3+ MDSCs were more abundant in patients with metastatic melanoma." (PMID 36175961, 2022).
melanoma (continued). "Ectopic expression of TYRO3 in the murine B16:F10 melanoma cell line was sufficient to increase MITF protein levels and resulted in increased nuclear localization of SOX10, a known regulator of MITF in melanoma." (PMID 30501104, 2018). "Ectopic expression of TYRO3 in the MCF10A breast cancer cell line induced AKT phosphorylation in the presence of GAS6 and treatment with GAS6 promoted AKT phosphorylation in the MDA-MB435 melanoma cell line, which expresses TYRO3 but not MERTK or AXL." (PMID 30501104, 2018). "Real time PCR examination of 8 AXL-positive tumors demonstrated that MER and TYRO3 transcripts were barely detectable and immunoblot analysis of representative melanoma cell lines confirmed mutual exclusion of AXL and TYRO3 and frequent co-expression of TYRO3 and MER." (PMID 27102439, 2016). "Co-activation of TYRO3 and MER was also frequently observed in these melanoma cell lines." (PMID 27102439, 2016). "Finally, the upregulation of AXL by SSMC is of particular interest, because AXL belongs to the TAM (Tyro3, AXL, MER) family of receptor tyrosine kinase involved in various cancers, including melanoma." (PMID 24344100, 2013). "In this study, we profile the expression of MER, TYRO3, and AXL among multiple human cancer cells, and assess induction of phosphorylated AKT (pAKT) by GAS6 and reversal by AXL/MER inhibitors in human melanoma G361 cells that were found to express high levels of MER and TYRO3, but not AXL." (PMID 32042425, 2020). "However, TYRO3 is aberrantly expressed in AML and multiple myeloma patient samples, and shRNA-mediated knockdown of TYRO3 in a melanoma model has a negative impact on cell survival in the majority of cell lines tested." (PMID 27834816, 2016).
breast carcinoma (18 papers, 2016 to 2026). "The TCGA breast cancer cohort study corroborated that the expression of the ferroptosis‐related protein SLC3A2 is positively correlated with TYRO3 expression, and high TYRO3 expression is associated with resistance to PD‐1 inhibitors in breast cancer patients." (PMID 41560416, 2026). "The TAM (Tyro3, Axl, and MerTK) family of receptor tyrosine kinases (RTKs) has recently been implicated in tumor growth, metastasis, and therapeutic resistance in breast cancer." (PMID 38927958, 2024). "The higher level of TYRO3 expression is associated with decreased overall survival in patients with colorectal, hepatocellular, and breast cancers." (PMID 34527446, 2021). "For example, Tyro3 has been linked to Akt in hepatocellular carcinoma, to regulate cell survival and Erk signalling to regulate proliferation in breast cancer." (PMID 31766614, 2019). "In addition, higher levels of TYRO3 expression have been associated with decreased overall survival in patients with colorectal, hepatocellular, and breast cancers." (PMID 30501104, 2018). "TYRO3 has also been implicated as a mediator of resistance to HER2 inhibitors in breast cancer." (PMID 30501104, 2018). "MERTK contributed to osteoblast dysfunction in osteolytic bone disease induced by breast cancer cells, whereas TYRO3 was bone-protective by promoting osteoblastogenesis and bone formation." (PMID 38203403, 2023). "Among these genes, ZFAND1, TYRO3, and TMEM206/PACC1 showed evidence of association with LoF variants for overall breast cancer." (PMID 35884425, 2022). "Of these twenty, three showed evidence of association with LoF variants for overall breast cancer (ZFAND1, TYRO3, TMEM206/PACC1), and a further six with breast cancer subtypes (DNAH11, PARP2, LAMC3, MTMR11, EPN3, SLC22A10)." (PMID 35884425, 2022). "Recently, TYRO3 was reported to be overexpressed in various cancers with poor prognoses, such as leukemia, melanoma, thyroid cancer, breast cancer, pancreatic cancer, and ovarian cancer." (PMID 34721022, 2021). "In bone, Gas6 was shown to stimulate mouse osteoclast function via Tyro3, involving activation of Erk and Erk signalling mediated Tyro3 regulation of proliferation in breast cancer." (PMID 31766614, 2019). "In breast cancer cells, high levels of phosphorylated TYRO3 correlated with sensitivity to siRNA-mediated TYRO3 inhibition." (PMID 30501104, 2018). "Overexpression of TYRO3 in the MCF10A breast cancer cell line decreased sensitivity to camptothecin." (PMID 30501104, 2018). "Inhibition of TYRO3 using siRNA decreased STAT3 phosphorylation in a HER2+ breast cancer cell line, suggesting stimulation of the JAK-STAT pathway in at least some cases." (PMID 30501104, 2018). "Higher levels of TYRO3 expression also correlated with poor response to therapy in patients with HER2-positive breast cancer in a meta-analysis of 22 publicly available microarray data sets." (PMID 30501104, 2018). "Abundant TYRO3 expression was also demonstrated in murine breast cancer tissue, while TYRO3 expression was minimal in normal mouse breast tissue." (PMID 30501104, 2018). "TYRO3 was also upregulated in a lapatinib-resistant derivative breast cancer cell line relative to the parental line and in an intrinsically-resistant breast cancer cell line treated with the HER2-targeted antibody trastuzumab." (PMID 30501104, 2018). "Mechanistically, anti-PD-1/PD-L1 treatment can significantly increase the expression of TYRO3 in breast cancer tissues, further elevate intracellular Nrf2 levels, reduce ROS generation, inhibit ferroptosis, create a tumor-promoting microenvironment, and confer resistance to anti-PD-1/PD-L1 therapy." (PMID 39664391, 2024). "Furthermore, we demonstrated that MERTK and TYRO3 play a role in the development of osteolytic lesions in preclinical models of breast cancer metastasis." (PMID 38203403, 2023).